TPH1 (tryptophan hydroxylase 1)
Diseases named in the same sentence as TPH1 in open-access papers (continued):
Sharing a sentence is not in itself a finding about the gene and the disease.
Obesity (32 papers, 2015 to 2026). Accumulation of substantial excess body fat. "Previously, obesity-associated increases in adipocyte TPH1 and the corresponding elevation in local adipose tissue 5-HT have been shown to alter the metabolism of both white and brown adipocytes." (PMID 40455408, 2025). "Another study showed that TPH1 gene-deficient mice fed a high-fat diet defended against obesity, insulin resistance, and non-alcoholic fatty liver disease (NAFLD) through a mechanism that involved greater energy expenditure in thermogenic brown adipose tissue." (PMID 36569060, 2022). "TPH1 deficient mice are protected from obesity and insulin resistance by elevation of brown adipose tissue activity." (PMID 26766570, 2016). "Given the numerous correlations between 5-HT, maintenance of lactation, and obesity, the objective of this study was to determine if a genetic deficiency for Tph1 would improve lactation outcomes in combination with HFD administration." (PMID 27603698, 2016). "High expression of Tph1 was recently reported in the human pituitary, and polymorphisms of Tph1 may be associated with an elevated risk for obesity, suicide behavior and schizophrenia in humans." (PMID 40362217, 2025). "Engraftment of mast cell-deficient mice with Tph1−/− mast cells or selective mast cell deletion of Tph1 enhances uncoupling protein 1 (Ucp1) expression in white adipose tissue and protects mice from developing obesity and insulin resistance." (PMID 31974364, 2020). "Tph1-deficient mice fed a high-fat diet are protected from obesity, insulin resistance and NAFLD." (PMID 33143653, 2020). "Besides the overproduction of cytokines such as IL-6 and TNF-α within the inflamed mammary microenvironment, which has deleterious effects on mammary gland function, obesity is linked to increased synthesis of serotonin in the mammary gland by upregulating tryptophan hydroxylase 1 (TPH1)." (PMID 40868103, 2025). "As such, use of mice deficient for Tph1 may mimic phenotypes of obesity in human patients." (PMID 27603698, 2016). "Mice depleted for TPH1 (Tph1-/-) are protected from HFD-induced obesity and related metabolic dysfunctions, showing less weight gain, lower adiposity, reduced insulin resistance, and liver steatosis compared to control mice." (PMID 41424854, 2026). "Previously, adipocyte TPH1 has been linked to increased adipose 5-HT, reduced brown adipose tissue (BAT) thermogenesis, and obesity." (PMID 40455408, 2025). "In accordance with these studies, high-fat diet promotes the overexpression of TPH1, which increases the serotonin levels, consequently promoting gluconeogenesis and lipogenesis, leading to obesity." (PMID 35581625, 2022). "Systemic tryptophan hydroxylase 1 inhibitors and a peripheral tryptophan hydroxylase 1 inhibitor (LP-533401) have been patented for use in treating diabetes and obesity." (PMID 35910256, 2022). "This pilot study has identified a large number of genes whose expression was changed significantly in human TPH1 cells following incubation with arecoline and MNPA and that are known to be associated with increased risks of obesity and T2D in humans." (PMID 34391409, 2021). "Our preliminary studies have identified a large number of genes relevant to obesity, T2D and metabolic syndrome whose expression was changed significantly in human TPH1 cells following incubation with betel-nut derived arecoline or with MNPA." (PMID 34391409, 2021). "The first and most evident is that the protection from obesity-induced glucose intolerance and insulin resistance is more dramatic in the KitTph1−/− mice compared to the Tph1 MCKO mice." (PMID 31974364, 2020). "Colonic EC cell numbers were significantly increased in the obese group of this study, confirming increased 5-HT content and TPH1/2 mRNA expression in long-term diet-induced obesity (DIO) mice." (PMID 30336615, 2018).
Obesity (continued). "Significantly elevated mucosal TPH1 expression in obese humans and elevated levels of circulating 5-HT in individuals with type 2 diabetes (T2D) or obesity has been reported." (PMID 30662430, 2018). "For example, Crane and coauthors showed in 2014 that Tph1 deficient mice have enhanced brown adipose tissue (BAT) thermogenesis and are resistant to obesity." (PMID 27603698, 2016). "Genetic inhibition of Tph1 protects or reverses the development of F diet induced obesity and dysglycemia via activation of UCP1-mediated thermogenesis in brown adipose tissue." (PMID 26766570, 2016). "A recent study using Tph1 KO mice reported that inhibition of peripheral Tph1 protects against diet-induced obesity and promotes BAT thermogenesis." (PMID 25864946, 2015). "Similarly, increased 5-HT levels and TPH1 activity are consistently observed in animal models of obesity 28,219-224." (PMID 41424854, 2026). "Moreover, genetic ablation of Tph1 can protect against high-fat diet-induced obesity and hepatic steatosis in mice." (PMID 40362217, 2025). "Both the density of enterochromaffin cells and the expression of tryptophan hydroxylase 1 are increased in human obesity; however, mechanisms driving such changes remain unknown." (PMID 35910256, 2022). "In conclusion, our findings identify a role for mast cell serotonin for energy balance and suggest that inhibition of mast cell Tph1 may represent a promising strategy for the targeted treatment of obesity and insulin resistance." (PMID 31974364, 2020). "Therefore, our findings, in two distinct mouse models as suggested support the conclusions that mast cell Tph1 protects against obesity induced insulin resistance by enhancing adipose tissue Ucp1 and whole body energy expenditure." (PMID 31974364, 2020). "This may be due to the fact that, in obesity conditions, there is a higher density of EC cells and an increased expression of TPH1; however, the role of 5-HT in obesity still remains unclear." (PMID 33081272, 2020). "Previous studies have indicated that genetic and chemical inhibition of the rate limiting enzyme regulating peripheral serotonin synthesis, tryptophan hydroxylase 1 (Tph1), enhances adipose tissue thermogenesis and protects mice against obesity and insulin resistance." (PMID 31974364, 2020). "TPH1 inhibition also protects mice from diet-induced obesity (DIO)." (PMID 30662430, 2018). "Interestingly, a very recent study demonstrates that knock-out mice for peripheral tryptophan-hydroxylase-1 (TPH1) are characterized by resistance to obesity which is explained by an increase in brown adipose tissue thermogenesis." (PMID 27456060, 2016). "Using two distinct mouse models we subsequently demonstrate that genetic deletion of Tph1 in mast cells reduces WAT serotonin and enhances WAT Ucp1 and whole-body energy expenditure; an effect associated with a reduction in high-fat diet-induced obesity, insulin resistance and NAFLD." (PMID 31974364, 2020). "Expression of TPH1 and PAX4 (a critical transcription factor in EC cell specification) is augmented in the duodenum and gastric antrum of obese subjects, while levels of plasma 5-HT and serum levels of the 5-HT metabolite, 5-HIAA, are associated with measures of human obesity." (PMID 30678223, 2019). "Thus, inhibiting Tph1-derived serotonin may be effective in reversing obesity and related clinical disorders such as NAFLD and type 2 diabetes." (PMID 25815090, 2015). "Mast cells regulate thermogenesis in adipose tissue by genetically removing tryptophan hydroxylase 1 (Tph1), which increases WAT mitochondrial uncoupling protein 1 (Ucp-1), protecting mice from obesity and IR." (PMID 41007770, 2025). "To evaluate the role of 5-HT in skeletal muscle in vivo, we generated skeletal muscle-specific Tph1-KO (Tph1 MKO) mice and evaluated their phenotypes in a diet-induced obesity model." (PMID 40451926, 2025).
Obesity (continued). "To assess the potential translational significance of obesity-induced adipose TPH2 expression, we examined the expression of TPH1 and TPH2 in lean and obese humans." (PMID 40455408, 2025). "The absence of gut-derived 5-HT, through pharmacological inhibition or genetic ablation of the rate-limiting enzyme for 5-HT synthesis in the gut, tryptophan hydroxylase 1 (TPH1), conveys protection from diet-induced obesity in mice." (PMID 31057420, 2019). "Additionally, adipose tissue-specific knockout of Tph1 or Htr2a (Tph1 FKO) mice fed an HFD exhibited reduced lipid accumulation, increased thermogenesis, and resistance to obesity." (PMID 36569060, 2022). "In addition to studies with TPH1-knockout mouse models, chemical inhibition of membrane-bound 5-HT receptor (5-HTR) signaling in the periphery also prevented mice from developing DIO, indicating that 5-HT promotes obesity via receptor-mediated signaling." (PMID 40455408, 2025). "Because serotonin cannot cross the blood-brain barrier (BBB), we focused on identifying new tryptophan hydroxylase type I (TPH1) inhibitors that act only in peripheral tissues for treating obesity and fatty liver disease without affecting the central nervous system." (PMID 35684355, 2022). "Consequently, this compound as a therapeutic agent is a useful non-BBB permeable TPH1 inhibitor that can act on the peripheral system while preventing obesity and fatty liver disease." (PMID 35684355, 2022). "Negative correlation between TPH1 and mitochondrial FAO in human adipose tissues bears out that inhibiting serotonin synthesis in adipose tissue can be a new therapeutic candidate for obesity therapy." (PMID 33671067, 2021).
colitis (27 papers, 2012 to 2026). Inflammation of the colon. "Research has found that the Tph1-deficient (Tph1−/−) mice, which have significantly reduced 5-HT levels in the gut, significantly ameliorates colitis severity in chemical induction models in chemically induced colitis." (PMID 40362261, 2025). "5-HT modulates the gut microbiota and alters colitis susceptibility in tryptophan hydroxylase 1 (Tph1)−/− mice." (PMID 39180723, 2024). "The severity of colitis is reduced in tryptophan hydroxylase 1 (TPH1, the key enzyme for the synthesis of 5-HT)-deficient mice." (PMID 35664068, 2022). "Tph1–/– mice with low 5-HT availability are tolerant to experimental colitis, while SERT-deficient animals with elevated 5-HT availability were susceptible to gut mucosal inflammation." (PMID 34638577, 2021). "On the other hand, host genetics related to the serotonergic pathway alter the gut microbial composition, as Tph1–/– mice have a different gut microbiota than that of Tph1+/+ mice, which is related to colitis susceptibility." (PMID 34638577, 2021). "Studies using Tph1-deficient mice showed that serotonin exacerbates the development of inflammatory disease (e.g., colitis) through promoting secretion of proinflammatory cytokines." (PMID 31963662, 2020). "Indeed, 5- HT has been implicated in worsening colitis as mice with tryptophan hydroxylase-1 knockout experienced reduced 5-HT in the GI tract and had reduced severity of DSS-induced colitis." (PMID 34983592, 2022). "In a TPH1 knock out (TPH1(−/−)) colitis mice model, that lack 5-HT produced by ECs, it was found that macrophage infiltration, IL-1β, IL-6, and TNFα production and colitis-associated colonic tissue damage were significantly reduced compared to the control (TPH1(+/+)) mice." (PMID 33807994, 2021). "Furthermore, when 5-HT stimulated DCs are transferred back into TpH1 deficient mice, there is significant increase in colitis severity and this is associated with higher myeloperoxidase (MPO) activity and pro-inflammatory cytokine (IL-1β and IL-6) levels." (PMID 25565996, 2014). "For instance, IDO1–/– mice are more susceptible to 2,4,6-trinitrobenzene sulfate-induced colitis whereas TpH1–/– mice show enhanced protection in response to DSS- or dinitrobenzene sulfonic acid-induced colitis, suggesting that while kynurenine is protective in the gut, 5-HT might be deleterious." (PMID 34540837, 2021). "Khan and colleagues demonstrated that mice were protected from colitis when mucosal 5-HT synthesis was diminished by the TPH inhibitor para-chlorophenylalanine or when Tph1 was knocked out in mice." (PMID 35664068, 2022). "In other experiments, DCs from TpH1−/− mice with DSS-induced colitis produced much lower amounts of IL-12p40, confirming a possible pro-inflammatory role of 5-HT on DCs." (PMID 34502396, 2021). "The difference between TpH1−/− mice TpH2−/− mice in the severity of colitis due to reduced levels of enteric 5-HT and reduced neuronal 5-HT, respectively, indicates that 5-HT can have different effects depending on the location." (PMID 34502396, 2021). "Mice engineered to lack components of the serotonergic system have revealed 5-HTs participation in gut disease: TPH1−/− mice exhibited reduced severity of chemical-induced colitis and an accompanying reduction in IL-1β, IL-6, and TNF-α." (PMID 30177522, 2018). "Restoration of 5-HT in TPH1−/− mice by administration of a 5-HT precursor (5-hydroxy-l-tryptophan) enhanced the severity of colitis." (PMID 28845184, 2017). "Past studies indicated the reduced severity of colitis in TPH1−/− mice as compared with wild-type mice after dextran sodium sulfate- and dinitrobenzenesulfonic acid-colitis." (PMID 28845184, 2017). "First, in DSS or DNBS colitis, reduction in the availability of mucosal 5-HT by deletion of Tph1, the enzyme that synthesizes 5-HT reduces the severity of inflammation." (PMID 28066160, 2016).
colitis (continued). "The severity of colitis is increased if the animals are treated with the 5-HT precursor 5-hydroxytryptophan to bypass Tph1 in the Tph1 KO mice." (PMID 28066160, 2016). "When animals were then supplemented with 5-hydroxytryptophan, a precursor to 5-HT synthesis that bypasses TPH1, the severity of the colitis was increased and pro-inflammatory cytokines were induced." (PMID 22403677, 2012). "Similarly, genetic deletion of Tph1 significantly reduces the severity of colitis, indicating that 5-HT exacerbates intestinal inflammation." (PMID 41465348, 2025). "As mice with depleted CD8+ T cells have increased Turicibacter58, and that is related to increased TNF-α59, this suggests that Tph1−/− mice may be protected from AR-induced colitis in part by altering the microbiome." (PMID 36539404, 2022). "This is supported by our findings that showed AR exposure did not influence susceptibility to colitis in Tph1−/− mice, while AR increased 5-HT and elevated the number of 5-HT+cells in the colon of C57BL/6 mice." (PMID 36539404, 2022). "Inhibitors of TPH1 were shown to exert beneficial effects in patients with colitis." (PMID 33466782, 2021). "In TPH1 deficient colitis mice, the severity of colitis and the level of IL-1β, IL-6, and tumor necrosis factor (TNF)-α was clearly reduced, and reloading 5-HT increased the severity of DSS-induced colitis." (PMID 32117308, 2020). "Also, reduction in 5-HT production with the selective TPH-1 inhibitor, telotristat etiprate, was protective in experimental colitis." (PMID 30177522, 2018). "Importantly, chronic exposure to AR does not influence colitis susceptibility in mice lacking tryptophan hydroxylase 1 (TPH1), the rate limiting enzyme for 5-HT biosynthesis." (PMID 36539404, 2022). "In addition, TpH1−/− mice with DNBS-induced colitis showed a reduced severity of the disease." (PMID 34502396, 2021). "AS-IV ameliorated colitis by downregulating IDO1 expression, while upregulating the expression of tryptophan hydroxylase 1 (TPH1), DDC, monoamine oxidase A (MAO-A), and the aryl hydrocarbon receptor (AhR), as well as inhibiting NF-κB p65 phosphorylation." (PMID 42195848, 2026). "Sost−/− mice exhibited increased intestinal Tph1 expression, while SKG mice showed reduced sclerostin and elevated Tph1 following curdlan-induced colitis-an effect dependent on the presence of intestinal microbiota." (PMID 41518441, 2026). "Specifically, mice lacking the rate-limiting enzyme for biosynthesis of 5-HT, tryptophan hydroxylase 1 (TPH1), showed significantly reduced severity of intestinal inflammation in both DSS and DNBS models of colitis." (PMID 38713616, 2024). "The DHR/RSV ratio also affected the serotonin pathway by controlling the expression of Tph1, SERT, and 5-HT7R leading to amelioration of colitis in mice." (PMID 35935130, 2022). "Oral administration of two peripheral TpH1 inhibitors, LP-920540 and telotristat etiprate, in mice with TNBS-induced colitis, resulted in improvement of the disease state and reduced expression of inflammatory cytokines and chemokines in the intestine." (PMID 34502396, 2021). "Germ-free mice colonized by gut microbiota from TpH1+/− mice after dextran sulfate sodium (DSS) treatment inducing colitis contained less Akkermansia muciniphila and demonstrated more severe colitis than germ-free mice colonized with TpH1−/− microbiota." (PMID 34502396, 2021). "The ability of AR exposure to induce colitis depends on the bioavailability of colonic 5-HT as evidenced by using mice lacking TPH1 or SERT." (PMID 36539404, 2022). "For example, in DSS-induced colitis, TpH1−/− mice produce lower levels of the pro-inflammatory cytokines TNF-α, IL-1β, and IL-6 and have reduced macrophage infiltration when compared to TpH1+/+ mice." (PMID 34502396, 2021).
colitis (continued). "Because of the knockout of TPH1, the concentration of 5-HT in the GI tract was significantly reduced, followed by alleviation in clinical severity and histological damage scores by pharmacological adjustment of mucosal 5-HT in DSS- or dinitrobenzene sulfonic acid (DNBS)-induced colitis." (PMID 34360695, 2021). "Additionally, in a mouse model of colitis, an inflammatory disease, animals lacking the rate-limiting enzyme for 5-HT synthesis (TPH1) displayed decreased severity of the disease, along with significantly lower macroscopic and histologic damage scores." (PMID 22403677, 2012).